JMY (junction mediating and regulatory protein, p53 cofactor)
Description:
In cytoplasm, acts as a nucleation-promoting factor for both branched and unbranched actin filaments. Activates the Arp2/3 complex to induce branched actin filament networks. Also catalyzes actin polymerization in the absence of Arp2/3, creating unbranched filaments. Contributes to cell motility by controlling actin dynamics. May promote the rapid formation of a branched actin network by first nucleating new mother filaments and then activating Arp2/3 to branch off these filaments. Upon nutrient stress, directly recruited by MAP1LC3B to the phagophore membrane surfaces to promote actin assembly during autophagy.
Synonyms: FLJ37870; WHAMM2; WHDC1L3
Tractability: PROTAC: UniProt records ubiquitination sites on it; ubiquitination databases record sites on it; its protein half-life has been measured.
Gene: Protein-coding gene on chromosome 5 (79,236,128 to 79,327,215, forward strand). Ensembl gene ENSG00000152409.
Subcellular location: Nucleus; Cytoplasmic vesicle; Cytoplasm, cytoskeleton; Endomembrane system; Cytoplasmic vesicle, autophagosome membrane
Subcellular location (Human Protein Atlas): Nucleoplasm
Gene Ontology:
Molecular function: microtubule binding; protein binding; Arp2/3 complex binding; transcription coactivator activity; actin binding
Biological process: cellular response to starvation; 'de novo' actin filament nucleation; actin polymerization-dependent cell motility; Arp2/3 complex-mediated actin nucleation; positive regulation of apoptotic process; regulation of transcription by RNA polymerase II; positive regulation of DNA-templated transcription
Cellular component: autophagosome membrane; cell leading edge; cytoplasmic vesicle; cytoplasm; nucleoplasm; nucleus; cytoskeleton; endomembrane system
Genetic constraint (gnomAD): Loss-of-function variants: 38 observed, 76.85 expected, observed/expected ratio (o/e) 0.49, 90% interval 0.38 to 0.65. The upper end of that interval is the gene's LOEUF score, 0.65, which puts it in group 2 of 6, group 1 being the genes least tolerant of losing a copy. Missense variants: 1,067 observed, 1,058.8 expected, observed/expected ratio (o/e) 1.01, 90% interval 0.96 to 1.06. Synonymous variants: 469 observed, 426.83 expected, observed/expected ratio (o/e) 1.1, 90% interval 1.02 to 1.19.
Homologues: Orthologues: chimpanzee JMY (99% identical), macaque JMY (98% identical), dog JMY (91% identical), pig JMY (90% identical), mouse Jmy (87% identical), rat Jmy (86% identical), guinea pig JMY (78% identical), tropical clawed frog jmy (63% identical), rabbit JMY (51% identical), zebrafish JMY (34% identical). Paralogues in human: WHAMM (32% identical), PRR11 (8% identical).
Diseases named in the same sentence as JMY in open-access papers:
JMY is named in the same sentence as 19 diseases in open-access papers, as found by Europe PMC text mining. Sharing a sentence is not in itself a finding about the gene and the disease. The quoted sentences say what the papers report.
breast carcinoma (3 papers, 2013 to 2023).
glioma (2 papers, 2020 to 2023). A benign or malignant brain and spinal cord tumor that arises from glial cells (astrocytes, oligodendrocytes, ependymal cells). "Targeting JMY could thus open the way to the development of new therapeutic strategies to improve the efficacy of radiotherapy and prevent glioma recurrence." (PMID 33128011, 2020). "The oncogenic effect of miRNA-21 in human glioma cells is implemented through the suppression of such tumor suppressor genes as TAp63, HNRPK, JMY, TOPORS, RECK, TP53BP2, TIMP3, PDCD4, and TGFBR2/3." (PMID 37033545, 2023).
Myocardial fibrosis (2 papers, 2021 to 2024).
Alzheimer disease (1 paper, 2022). A progressive, neurodegenerative disease characterized by loss of function and death of nerve cells in several areas of the brain leading to loss of cognitive function such as memory and language. "Other genes in analysis (JMY, ZNF525, and COBLL1) were not previously associated with Alzheimer’s disease." (PMID 35626321, 2022).
ankylosing spondylitis (1 paper, 2013). An autoimmune chronic inflammatory disorder characterized by inflammation in the vertebral joints of the spine and sacroiliac joints. "We aim to examine the influence of JARID1A, JMY, and PTGER4 polymorphisms on the susceptibility to and the severity of ankylosing spondylitis in Chinese ethnic majority Han population." (PMID 24069348, 2013).
B-cell lymphomas (1 paper, 2021). "Interestingly, JMY expression also appears to be lost in several B-cell lymphomas and invasive carcinomas." (PMID 33872315, 2021).
chronic myelogenous leukaemia (1 paper, 2023).
glioblastoma (1 paper, 2016). The most malignant astrocytic tumor (WHO grade IV).
Immunodeficiency (1 paper, 2019). Failure of the immune system to protect the body adequately from infection, due to the absence or insufficiency of some component process or substance. "Besides, the expression of JAM3 is decreased in this progression and its defection may cause immunodeficiency in mice, which in turn reduces tumor immune surveillance; in the second pathway, homeobox protein NKX2-5 upregulates target genes PAP2C and JMY, which can lead to cancer cell apoptosis." (PMID 31126066, 2019).
melanoma (1 paper, 2020). A malignant, usually aggressive tumor composed of atypical, neoplastic melanocytes. "Thus, at least in this melanoma cell line, 2D migration relies primarily on the WAVEs and WHIMP without major contributions from N-WASP or JMY." (PMID 32196488, 2020).
osteosarcoma (1 paper, 2021). A usually aggressive malignant bone-forming mesenchymal neoplasm, predominantly affecting adolescents and young adults. "For further gauging the effects of JMY on apoptosis in different human cell lines, we targeted JMY using siRNAs in U2OS osteosarcoma cells and HeLa adenocarcinoma cells." (PMID 33872315, 2021).
tumor (9 papers, 2013 to 2023). "Given that JMY reduced DNA damage accumulation, increased resistance to chemotherapeutic drugs, and reduced overall mutation count, we hypothesised that tumours with higher JMY expression might exhibit a more aggressive phenotype resulting in poorer patient survival." (PMID 37142657, 2023). "In patient samples, we found that across all cancer types (TCGA pan cancer), tumours with lower JMY mRNA expression or homozygous deletion contained an increased mutation count." (PMID 37142657, 2023). "We chose EGFL7 as our candidate for next experiments due to the tumor suppressor role of JMY in ccRCC." (PMID 30953521, 2019). "All these characteristics taken together imply that JMY possesses both tumour suppressive and tumour metastasis promoting capabilities." (PMID 29857553, 2018). "In this context, specific targeting of JMY could provide new therapeutic perspectives to limit radiation-induced migration of GSCs and hence prevent tumor recurrence following radiotherapy." (PMID 33128011, 2020). "While JMY’s putative tumour promoting role could be seen in its ability to increase cell motility and downregulate cadherin proteins." (PMID 29857553, 2018).
cancer (7 papers, 2018 to 2023). A tumor composed of atypical neoplastic, often pleomorphic cells that invade other tissues. "Similarly, the functions of WHAMM and JMY in autophagy could enable cancer cells to better survive in diverse physiological environments and in response to chemotherapy." (PMID 33872315, 2021).
JMY also shares sentences with these, for which no sentence is quoted: adenocarcinoma (1 paper); invasive carcinoma (1); myocardial infarction (1); neuroblastoma (1); type 2 diabetes (1); velocardiofacial syndrome (1).